UPP1 (uridine phosphorylase 1)
Diseases named in the same sentence as UPP1 in open-access papers (continued):
Sharing a sentence is not in itself a finding about the gene and the disease.
tumor (continued). "However, the treatment of PD-L1 antibodies could partially alleviate the impaired ability of OT-1 CD8 + T cells to eliminate UPP1-overexpressing LLC-OVA tumor cells." (PMID 38331898, 2024). "Notably, the administration of anti-PD-L1 immunotherapy to mice with UPP1-inhibited tumors showed a further increase in the inhibitory effects on tumor growth, suggesting that inhibiting UPP1 expression increased the sensitivity of tumors to anti-PD-L1 immunotherapy." (PMID 38331898, 2024). "As the upregulation of UPP1 in tumor cells can significantly alter the functional state of CD8 + T cells, we next sought to determine whether inhibiting UPP1 expression in tumor cells could restore the cytotoxicity of CD8 + T cells and enhance the sensitivity to immunotherapy." (PMID 38331898, 2024). "Considering the enrichment of immune checkpoints in the cell-cell interaction networks between UPP1high tumor cells and T cells, we next focused on whether high UPP1 expression in tumor cells could lead to the upregulation of immune checkpoints, thereby promoting immune evasion." (PMID 38331898, 2024). "However, upon inhibiting UPP1 expression, tumor proliferation was suppressed." (PMID 38331898, 2024). "Similarly, flow cytometry counting of alive tumor cells after co-culture revealed that PD-L1 blockade could reduce the proportion of UPP1-overexpressing LLC-OVA tumor cells that survived the attack of OT-1 CD8 + T cells." (PMID 38331898, 2024). "In conclusion, Erk activation is induced by HGF directly, enhancing tumor proliferation; however, the enhancement of proliferation is considered to accelerate the misincorporation of 5-FU metabolites into DNA and RNA, which is further augmented by UPP1 overexpression, induced by HGF." (PMID 36012373, 2022). "The upregulated UPP1, which catalyzes the degradation of uridine to uracil and ribose-1-phosphate, counteracts UMP synthesis, making the tumor cells more dependent on de novo synthesis of UMP." (PMID 41243973, 2025). "Uridine phosphorylase 1 (UPP1), an enzyme involved in pyrimidine metabolism, has been found to be elevated in H. pylori-infected gastric tissue within tumor cell populations." (PMID 41305005, 2025). "In CRC, HOTAIR upregulated the metabolic enzymes UPP1 by recruiting EZH2, thereby promoting the tumor progression, suggesting a novel metabolic axis for CRC therapy." (PMID 38696320, 2024). "Mechanistically, HOTAIR upregulated the metabolic enzymes UPP1 by recruiting histone methyltransferase EZH2, thereby increasing the tumor progression." (PMID 38696320, 2024). "Besides, the assessment of cytotoxic markers, Perforin and Granzyme B, in OT-1 CD8 + T cells showed that the upregulation of UPP1 in tumor cells significantly reduced the cytotoxicity of OT-1 CD8 + T cells, while this killing ability could be partially restored by blocking PD-L1." (PMID 38331898, 2024). "By contrast, UPP1-high cell lines and UPP1-high PDA tumours from patients displayed a profound downregulation of other metabolic pathways, notably amino acid, fatty acid and glutathione metabolism." (PMID 37198494, 2023). "Whole-body genetic deletion of Upp1 did not influence the time to clinical endpoint (one primary tumour reaching 15 mm in diameter), nor did it influence the final primary tumour burden of MMTV-PyMT mice (Fig. EV6A)." (PMID 40702342, 2025). "Increased Upp1 was detected in BM neutrophils from tumour-bearing MMTV-PyMT mice compared to non-tumour-bearing FVB/N controls." (PMID 40702342, 2025). "Of note, neither BAU treatment nor deletion of Upp1 influenced neutrophil motility in the lungs of non-tumour-bearing mice." (PMID 40702342, 2025). "Because BAU did not influence primary tumour growth, this provided the opportunity to assess the ability of UPP1 to influence the pre-metastatic microenvironment of the lung." (PMID 40702342, 2025).
tumor (continued). "Furthermore, incubation of BM neutrophils with GM-CSF significantly increased their Upp1 expression (Fig. EV2E), suggesting that tumour-induced alterations in cytokine expression can stimulate increased Upp1 expression." (PMID 40702342, 2025). "This indicated that Upp1 was upregulated in neutrophils from the lungs of MMTV-PyMT tumour-bearing mice, and not in other immune cell types." (PMID 40702342, 2025). "Collectively, these data suggest that the increased levels of circulating uracil previously characterised are not due to tumour-specific alterations in Upp1 expression." (PMID 40702342, 2025). "To understand whether this neutrophil-specific Upp1 upregulation was unique to lung neutrophils, we also assessed Upp1 in splenic cells isolated from MMTV-PyMT tumour-bearing mice (Data Ref:)." (PMID 40702342, 2025). "This analysis revealed that seven cell populations exhibited a significant correlation with poorer patient outcomes, including tumor cell cluster 3 (highly expressing S100A2), cluster 8 (TK1), cluster 10 (PTTG1), cluster 12 (IGFBP5), cluster 13 (ISG15), cluster 16 (UPP1), cluster 17 (IL13RA2)." (PMID 38331898, 2024). "Bioinformatics analysis of unpaired samples revealed that UPP1 expression in tumor tissues was significantly higher than that in non-tumor tissues." (PMID 38385072, 2024). "We found that UPP1 is highly expressed in PDA tumours compared with non-tumoural samples, and also in liver metastasis compared with primary tumours." (PMID 37198494, 2023). "Consistently, tumours expressed high UPP1 compared with non-tumoural tissues, and UPP1 expression correlated with poor survival in cohorts of patients with PDA." (PMID 37198494, 2023). "However, the UPP1-KO tumours had lower vessel density (CD31) and more anti-tumour T cell infiltration (CD8 T cells)." (PMID 37198494, 2023). "Finally, UPP1 deletion restricted the ability of PDA cells to use uridine and blunted tumour growth in immunocompetent mouse models." (PMID 37198494, 2023). "Interestingly, we find that levels of pentose phosphates are not altered in Upp1−/− tumours, nor are pentose phosphates altered in the serum of neutrophil-depleted tumour-bearing mice." (PMID 40702342, 2025). "However, to study whether the physical presence of neutrophils might influence T-cell proliferation in a way that was dependent on their UPP1 status, we measured T-cell proliferation in the presence and absence of neutrophils from tumour-bearing MMTV-PyMT mice that were either Upp1+/+ or Upp1−/−." (PMID 40702342, 2025). "However, it’s noteworthy that the role of UPP1 in LUAD is relatively less studied, and its involvement in tumor progression is not yet fully elucidated." (PMID 38331898, 2024).
cancer (28 papers, 2009 to 2026). A tumor composed of atypical neoplastic, often pleomorphic cells that invade other tissues. "Uridine phosphorylase 1 (UPP1) is implicated in numerous cancers, yet lacks comprehensive evaluation across cancer types." (PMID 41731765, 2026). "Paradoxically, expression levels of UPP1 are consistently upregulated in cancer—a disease canonically associated with increased formation of macromolecules rather than their disassembly." (PMID 40702342, 2025). "Collectively, these data suggest that UPP1-dependent generation of uracil is associated with metastasis, and poor prognosis, in several cancer types." (PMID 40702342, 2025). "Notably, high UPP1 expression was associated with poor prognosis in 8 cancer types (OS: hazard ratios >1, P <.05)." (PMID 41731765, 2026). "UPP1 overexpression is associated with poor prognosis and cancer progression." (PMID 38385072, 2024). "This study analyzes the expression, genetic alterations, DNA methylation, and prognostic significance of UPP1 across 33 cancer types using multiple cancer genomics databases." (PMID 41731765, 2026). "UPP1 serves as a significant oncogenic factor in various cancers, highlighting its value as a prognostic biomarker and a potential therapeutic target." (PMID 41731765, 2026). "Promoter methylation of UPP1 varied significantly across cancers, correlating inversely with expression levels." (PMID 41731765, 2026). "Across analysis, UPP1 was consistently upregulated in malignant and H. pylori-positive epithelium, increasing along pseudotime toward cancer-like states." (PMID 41737224, 2026). "We utilized databases such as TIMER, GEPIA, UALCAN, cBioPortal, and Kaplan-Meier Plotter to conduct a systematic analysis of UPP1 involving gene expression, genetic alteration patterns, promoter methylation, and survival impact in various cancers." (PMID 41731765, 2026). "This pan-cancer study aims to elucidate UPP1's roles and establish its potential as a biomarker and therapeutic target." (PMID 41731765, 2026). "Glutaminase inhibition then suppresses cancer cell growth, elevates intracellular ROS, and concurrently upregulates uridine phosphorylase 1 (UPP1), which promotes 5-FU conversion to its active form and thereby enhances 5-FU efficacy." (PMID 41488637, 2025). "Collectively, our data show that neutrophils are a significant source of UPP1 in cancer, and that UPP1 can influence the immunosuppressive and motile behaviour of neutrophils and ECM deposition in the lung." (PMID 40702342, 2025). "Given that 5-FU, a commonly used chemotherapeutic agent in PC, targets pyrimidine metabolism, UPP1 not only influences drug response but also supports the metabolic adaptation of cancer cells—positioning it as a dual therapeutic target." (PMID 40358702, 2025). "Many of these genes, such as VIM, FOSL2, PTN, GPR3, SIAH2, UPP1, S100A2 are associated with cell migration and epithelial-mesenchymal transition (EMT) in several cancers." (PMID 36850002, 2023). "We conclude that the endogenous expression of UPP1 is necessary and sufficient to support the growth of cancer cells on uridine." (PMID 37198474, 2023). "Uridine phosphorylase 1 (UPP1) is a dimeric enzyme that plays an indispensable role in pyrimidine salvage as well as uridine homeostasis and is upregulated in various cancers, including LUAD." (PMID 36186123, 2022). "UPP1 is a pyrimidine degrading enzyme that contributes to cancer cell death in response to drugs that induce lethal catabolic stress." (PMID 36428689, 2022). "Expression levels of several previously reported genes implicated in cancer development and progression were altered, such as DDIT3, GATA6, UPP1, FAT3." (PMID 26158411, 2015). "Among the 21 validated genes, the strikingly decreased transcription of PTPRG and AMN1 and increased transcription of UPP1 potentially support data on cell cycle disturbances relevant to cancer, stem cell and neurodegenerative diseases' research." (PMID 19763259, 2009).
cancer (continued). "UPP1, a key enzyme in the pyrimidine salvage pathway, may contribute to the altered nucleotide metabolism characteristic of cancer, thereby supporting rapid cellular proliferation." (PMID 40358702, 2025). "Assessment of UPP1 expression in fibroblasts found that although fibroblasts can express UPP1, levels are not upregulated in cancer-associated fibroblasts by comparison to their normal counterparts (Data Ref:)." (PMID 40702342, 2025). "High expression of TCN1 and UPP1 was present in many malignant cancers." (PMID 35073659, 2024). "Thus, our findings highlight the potential therapeutic value of targeting UPP1 in combination with immune checkpoint blockade, offering a potential avenue for enhancing the efficacy of cancer immunotherapies." (PMID 38331898, 2024). "This suggested the potential of uridine phosphorylase 1 (UPP1) as a new target for cancer therapy." (PMID 39534557, 2024). "Moreover, a recent study provided further insights into the role of UPP1 in cancer, especially under glucose-restricted conditions." (PMID 38331898, 2024). "Indeed, UPP1 overexpression has been observed, and UPP1 is reported to be an oncogene that is related to cancer progression and prognosis." (PMID 36186123, 2022). "The extensive data have proven UPP1 is an efficient prognosis marker for cancer." (PMID 33498463, 2021). "UPP1, the enzyme responsible for the phosphorolysis of uridine into uracil and ribose-1 phosphate, is a key nucleotide metabolism enzyme that has been the subject of several papers in recent years, in part due to its consistent and strong relationship with decreased survival in several cancer types." (PMID 40702342, 2025). "However, Upp1 was proposed to fulfill a different role in cancer, related to energy metabolism." (PMID 40394416, 2025). "Interestingly, the increase in abundance of Upp1 seen in the inflamed samples is consistent with the development of many cancers, indicating a degree of oncogenesis may have begun." (PMID 35466239, 2022). "Expression of several genes known to be involved in cancer progression were identified by this method, including HMGA2, FHL1, SLC2A3, ADAMTS1, UPP1, and TGM2." (PMID 32054828, 2020). "Additionally, the UPP1 level is also positively correlated with the levels of TNF-α and IL-1β in most cancer types, consistent with our findings suggesting that both cytokines are required to upregulate UPP1." (PMID 41243973, 2025). "Finally, as shown in our study with UPP1-CRISPRa and PDA, AMT can be customized to fit different cancer metabolic programs." (PMID 39905264, 2025). "Our results highlight the essential role of HOTAIR in pan-cancer and uridine bypass, suggesting that the HOTAIR/EZH2/UPP1 axis might be a novel target for overcoming CRC." (PMID 38696320, 2024). "Also, mRNA expression levels of CHOP and UPP1 were induced upon combined NEN and amitriptyline, resembling the response observed in cancer cell lines (Fig EV5B)." (PMID 33665961, 2021). "Uridine phosphorylase 1 (UPP1) functions in its phosphorolysis of uridine to uracil and ribose-1-phosphate, which is considered as an indispensable metabolic enzyme in the pyrimidine salvage biological processes and is upregulated in many cancers, including CRC." (PMID 38696320, 2024). "Our solid tumour PRISM cancer cells collection did not include cells of the immune lineage, where UPP1 is expressed at high levels, so we asked whether immune cells exhibit the capacity to metabolize ribose from uridine either at baseline or in a transcriptionally regulated manner." (PMID 37198474, 2023).
neurological disorders (1 paper, 2009). "In support of that, TNF-α and IL-1, inducers of UPP1, alter lipid metabolism and stimulate production of eicosanoids, ceramide and reactive oxygen species that potentiate CNS injuries and certain neurological disorders." (PMID 19763259, 2009).
UPP1 also shares sentences with these, for which no sentence is quoted: infection (2 papers); oral squamous cell carcinoma (2); respiratory allergy (2); benign glioma (1); colon cancer (1); colorectal tumours (1); contact dermatitis (1); esophageal cancer (1); head and neck cancer (1); hydronephrosis (1); inflammatory skin disease (1); liver failure (1); lung carcinoma (1); metastasis (1); neurodegenerative disease (1); nicotine addiction (1); oligodendroglioma (1); ovarian carcinoma (1); preeclampsia (1); steatosis (1).